GCG (glucagon)
Diseases named in the same sentence as GCG in open-access papers (continued):
Sharing a sentence is not in itself a finding about the gene and the disease.
diabetes (continued). "In people with diabetes, SGLT2 inhibitor-induced glycosuria modestly increases blood ketone levels by increasing the glucagon:insulin ratio." (PMID 37159343, 2023). "Since its discovery, there have been intensified scientific efforts to optimize the function of this hormone, which has also increased the study of other hormones, such as glucagon, resulting in an ostensible improvement in the survival of patients with diabetes mellitus (DM)." (PMID 37675359, 2023). "This enhancement of glucagon secretion, which was also confirmed in healthy subjects and subjects with T2DM, hinders the clinical use of GIP agonists for diabetes treatment." (PMID 37729025, 2023). "The source of data was IQVIA-MIDAS (units of glucagon sold), while data on persons with type 1 diabetes in countries were derived from IDF Diabetes Atlas." (PMID 36550552, 2022). "Following induction of diabetes, colocalization of EEA1 with glucagon (PCC 0.03 ± 0.07) or Stmn2 (PCC 0.04 ± 0.07) still remained very weak." (PMID 34923907, 2022). "Individuals with type 2 diabetes mellitus (T2D) and/or non-alcoholic fatty liver disease (NAFLD) exhibit hepatic glucagon resistance, which in turn contributes to worsening of steatosis by blocking the beneficial effects of glucagon on hepatic fat." (PMID 35718339, 2022). "Further research on islet α cells, glucagon, and GCGR signaling pathways is expected to provide a basis for developing new strategies for diabetes prevention." (PMID 35784565, 2022). "Nevertheless, the glucagon positive cell number in the diabetes group was similar to the control group (P > 0.05), both GQD and metformin significantly increased the glucagon cell number of the diabetic rats (p < 0.05)." (PMID 35858880, 2022). "This study reported impaired suppression of glucagon secretion in patients with chronic pancreatitis and IGT or diabetes in response to an oral glucose tolerance test." (PMID 35819935, 2022). "These targets are enriched in multiple pathways related to type 2 diabetes mellitus, including adipocytokine, AMPK, TNF, HIF-1, PI3K-AKT, NOD and TOLL-like receptors, mTOR, glucagon, and insulin signaling pathways." (PMID 36160451, 2022). "In conclusion, BHB is responsible for the inhibitory effect of HADHA on hepatic glucagon response, suggesting that HADHA activation or BHB elevation by pharmacological intervention hold promise in treating diabetes." (PMID 35046401, 2022). "In type 2 diabetes mellitus (T2DM), insulin resistance and defective insulin release are often accompanied by increased glucagon levels, which further mobilize glucose from the liver." (PMID 36104518, 2022). "We report here that GLDC is over‐expressed in animal models of diabetes, obesity, and nutritional stress, and that GLDC gene expression is strongly regulated by metabolic hormones, especially glucagon." (PMID 34342168, 2021). "Type 2 diabetes mellitus (T2DM) and non-alcoholic fatty liver disease (NAFLD) are characterised by high GCG levels and GCG resistance; manipulation of GCG signalling is a potential pharmacological strategy for the treatment of these conditions." (PMID 34271220, 2021). "Autophagy is a potential mechanism through which arsenic exposure induces adverse health outcomes including type 2 diabetes mellitus (T2DM); hepatic autophagy impacts cellular metabolism and affects glucagon and insulin levels." (PMID 34243768, 2021). "GCG, IRS1, VEGFA, STAT3, CCL2, CASP3, and APOE as diabetes mellitus-related proteins and SREBF1, LPL, PPARA, APOB, GPT, MAPK8, and FASN as NAFLD-specific proteins were identified as possible discriminating factors between the two studied diseases." (PMID 35154608, 2021). "Importantly, glucagon excess is also present in most patients hospitalized with diabetic ketoacidosis, including those with severe type 2 diabetes (T2D) and hyperglucagonemia may increase the severity of diabetes and thus insulin requirements." (PMID 33753784, 2021).
diabetes (continued). "In the absence of pre-existing diabetes, hyperglycemia can develop secondary to physiologic stress, which causes increased sympathetic stimulation and a subsequent rise in circulating catecholamines, cortisol, glucagon, and growth hormone levels, thereby inducing hepatic gluconeogenesis." (PMID 34206813, 2021). "Diabetes related biomarkers, gastric inhibitory polypeptide (GIP), leptin, glucagon, and inflammatory cytokines interleukin 4 (IL-4) and IL-5, 10 and 12, IFN-g and TNF-α were significantly affected by HFB diet." (PMID 34441468, 2021). "The pathophysiology of type 2 diabetes mellitus (T2DM) is characterized by not only insulin resistance and beta cell dysfunction, but also the abnormal regulation of glucagon secretion." (PMID 32215330, 2020). "Diabetes mellitus (DM) is a heterogeneous group of physiological disorders characterized by hyperglycemia resulting directly from insulin resistance, inadequate insulin secretion, or excessive glucagon secretion." (PMID 32542584, 2020). "Recently, we have shown that Ss infection has a protective role on diabetes-related parameters and that Ss infected T2DM individuals showed decreased levels of insulin and glucagon that increased following therapy." (PMID 33042134, 2020). "Vildagliptin suppressed an inappropriate glucagon response to an oral glucose challenge in patients with T2DM, to a mixed meal challenge in patients with T2DM and type 1 diabetes mellitus, and to a mixed meal challenge in subjects with IGT and IFG." (PMID 31781045, 2019). "Here, we have identified the glucagon interactome in α-TC1-6 cells after chronic exposure to extremely high glucose (25 mM), which, in diabetes, paradoxically increases glucagon secretion from pancreatic alpha cells." (PMID 30713523, 2018). "Plasma glucagon and beta hydroxybutyrate levels of MIDY pigs were chronically elevated, reflecting hallmarks of poorly controlled diabetes in humans." (PMID 28752056, 2017). "On the other hand, the α-cell specific Siglec-3 showed a substantial increase in diabetes upon normalization against cyclophilin (PPIA), glucagon or SAT2 (induced to 5.15-, 4.29-, 5.52-fold, respectively in individuals with T2D, vs. non-diabetic controls)." (PMID 28378743, 2017). "GIP-based therapy for diabetes was abandoned because the insulinotropic effect of GIP is reduced and GIP-dependent postprandial glucagon production is increased in type 2 diabetes." (PMID 27483245, 2016). "In young (4 wk old) diabetes-prone NOD mice, glucagon-, insulin- and somatostatin-positive cells comprised most of the islet area (84.9±1.8%)." (PMID 25101835, 2014). "In several murine models of diabetes, acute and chronic dosing with GRA1 significantly reduced blood glucose concentrations and moderately increased plasma glucagon and glucagon-like peptide-1." (PMID 23185367, 2012). "The hyperlipidemia associated with diabetes may result from an accelerated hepatic triglyceride biosynthesis and the release of VLDL without an increase in its rate of clearance from the blood by lipoprotein lipase, which is dependent on the insulin/glucagon ratio." (PMID 23190471, 2012). "Recent studies also found that a dysfunction of glucagon secretion and impaired incretin system contribute to hyperglycemia in T2DM, which will provide untapped potential for the betterment of diabetes care." (PMID 22645689, 2012). "In type 2 Diabetes Mellitus (T2DM), glucagon levels are elevated in both the fasted and postprandial states, which contributes to inappropriate hyperglycemia through excessive hepatic glucose production." (PMID 21631939, 2011). "Although glucagon levels were higher in the subjects without diabetes, this was attributed to the lack of glucagon counterregulation to hypoglycemia in the T1D group, not to any response variation to the amino acids." (PMID 41602572, 2026).
diabetes (continued). "In individuals without diabetes, a decline in endogenous insulin secretion (from β cells) and a rise in glucagon secretion (from α cells) limit hypoglycemia when blood glucose levels decline to approximately 3.5 mmol/L." (PMID 41502124, 2026). "Protein ingestion normally stimulates alpha and beta cells to produce glucagon and insulin, respectively in people not living with diabetes." (PMID 41602572, 2026). "We found that bi-hormonal cells containing glucagon/insulin, insulin/somatostatin, or glucagon/somatostatin each represented around 2–3% of total islet endocrine cells in individuals without diabetes or other metabolic diseases." (PMID 39791735, 2025). "We propose that chronic hyperglucagonemia and tissue-specific glucagon resistance represent not secondary phenomena, but primary upstream drivers of organ dysfunction in diabetes." (PMID 40822953, 2025). "Metabolic regulation: Insulin signaling pathway showed nodal connections with both glucagon signaling and inflammatory pathways (IL-17 signaling, TNF signaling), proposing a unique therapeutic strategy for diabetes complications via metabolic-inflammatory crosstalk regulation." (PMID 41295287, 2025). "Here, 3-dimensional (3D) analyses of pancreata from control persons without diabetes (ND) revealed heretofore underappreciated frequencies (approximately 50%) of insulin-positive (INS+) glucagon-negative (GCG-) islets." (PMID 40502779, 2025). "The lack of insulin production and glucagon secretion makes glycemic control difficult in this form of diabetes, which gives it the name “brittle” diabetes." (PMID 40559084, 2025). "Immunofluorescence microscopy was performed for insulin, glucagon, and somatostatin presence on paraffin-embedded sections of pancreata from 20 donors without diabetes aged between 11 days and 79 years of age." (PMID 39791735, 2025). "While insulin is the primary focus in diabetes treatment, the significance of glucagon should not be overlooked." (PMID 39996055, 2025). "Post-mortem pancreatic sections from 24 people with CF and 10 organ donors without CF or diabetes were stained for insulin/glucagon/vimentin and Sirius red/fast green with collagen distribution assessed semi-quantitatively and quantitatively (non-CF)." (PMID 39836539, 2025). "According to previous reports, malnourished patients with type 2 diabetes mellitus (T2DM) exhibit elevated levels of glycated hemoglobin (HbA1c), random blood glucose (RBG), insulin, and glucagon, likely due to reduced insulin sensitivity and increased insulin resistance." (PMID 40469675, 2025). "Therapies based on GCG and GLP-1 have been approved for the treatment of diabetes and obesity." (PMID 41280890, 2025). "In islets from organ donors without diabetes (that is, ND), lowering glucose from 6 mM to 1 mM consistently stimulated glucagon secretion by 147 ± 45% (P < 0.0001 by one-tailed t-test)." (PMID 39313541, 2024). "However, the mRNA expression levels of GCG were comparable between the HF1478 group and the diabetes group (P>0.05)." (PMID 38934548, 2024). "In the absence of diabetes, several counter regulatory hormones rise when glucose levels drop below a hemostatic setpoint (−5.0 mmol/L), including glucagon, cortisol, growth hormone and catecholamines." (PMID 38510652, 2024). "Insulin and glucagon were 48% and 29% higher, respectively, in the incident diabetes group compared with the non-diabetes group; however, we found no temporal trends for these biomarkers." (PMID 39078488, 2024). "Also, for glucagon, an elevation is reported up to 6 months after RYGB, and GIP is mostly decreased after RYGB in individuals with diabetes mellitus." (PMID 39203840, 2024). "As a result, individuals with T1D display similar levels of fasting glucagon to those without diabetes, despite having elevated fasting blood glucose." (PMID 38612880, 2024).
diabetes (continued). "For example, I learned that glucagon should be given to a hypoglycemic patient with diabetes (sub-theme: awareness of lack of knowledge and misconceptions; agreeing with their peers’ arguments)." (PMID 38403641, 2024). "More recently, studies have shown that inducible elimination of glucagon action by administration of a GCGR monoclonal antibody (GCGR-Ab) enhances beta cell survival, regeneration, and function in pre-clinical models of type 1 (T1D) and type 2 (T2D) diabetes." (PMID 39433176, 2024). "Diabetes mellitus (DM) represents a group of physiological dysfunctions characterized by hyperglycemia, resulting from insulin resistance (as seen in type 2 diabetes mellitus-T2DM), inadequate insulin secretion/production, or excessive glucagon secretion (in type 1 diabetes mellitus-T1DM)." (PMID 39070316, 2024). "In addition, the mRNA expression levels of glp-1, GCG, and PC1/3 in HF2123 and HF2130 groups were significantly higher than those in the diabetes group (P < 0.05)." (PMID 38934548, 2024). "In a separate experiment conducted on Type 2 Diabetes Mellitus (T2D) human donor alpha cells, the results demonstrated that glucagon exocytosis is not prevented by hyperglycemia or insulin inhibition." (PMID 39594662, 2024). "Nevertheless, no game tackles the complexity of diabetes management from such a wide perspective as MyDiabetic, in which unique features such as glucagon administration and ketoacidosis modules are included." (PMID 38713496, 2024). "In individuals without diabetes, the basal glucagon concentration maintains approximately half of the basal hepatic glucose production, which regulates fasting plasma glucose levels." (PMID 39149119, 2024). "Fasting glucagon secretion rates and glucagon secretion rates during the hyperglycemic clamp were unchanged by exendin 9-39 infusion in people without diabetes." (PMID 37751301, 2023). "PCPs provided hypoglycaemia anticipatory guidance in 50 visits (21%) that focused on holding diabetes medications while fasting and carrying glucose tabs; avoiding driving and glucagon were not discussed." (PMID 38076413, 2023). "Type 3c is often called brittle diabetes because glucose control is especially challenging absent an appropriate beta cell (insulin) or alpha cell (glucagon) response." (PMID 36979645, 2023). "Recent studies have identified G protein‐coupled receptor 40 (GPR40) as a promising target for treating type 2 diabetes mellitus, and GPR40 agonists have several superior effects over other hypoglycemic drugs, including cardiovascular protection and suppression of glucagon levels." (PMID 37404062, 2023). "By contrast, in diabetes where the α cells are dysfunctional, excessive RAGE ligands and islet RAGE upregulation leads to chronic activation of RAGE and the pathological suppression of glucagon expression." (PMID 37558746, 2023). "In fasting and diabetes, nuclear CD38 prompts the production of ADP-ribose, triggering changes essential for generating the sustained calcium ion signals vital for responding to glucagon." (PMID 37394593, 2023). "There was also no counselling about glucagon, despite recommendations in diabetes guidelines for glucagon prescription and caregiver education for all patients at risk for hypoglycaemia." (PMID 38076413, 2023). "In addition, the treatment with the two drugs decreased the incidence of type 1 diabetes mellitus, T2DM, insulin resistance, glucagon signaling pathway, and nonalcoholic fatty liver disease (NAFLD)." (PMID 36778868, 2023). "This is likely explained by the fasting glucagon concentrations, which increased to a greater extent than was observed in people without diabetes and are inappropriate for the prevailing (higher) glucose concentrations." (PMID 37751301, 2023). "In GCK-MODY patients, the threshold for glucose to suppress glucagon is higher than that in people without diabetes." (PMID 37159865, 2023).
diabetes (continued). "In terms of diabetes compensation, repeated HBOT throughout the year reduces insulin consumption, recovers residual insulin secretion, and suppresses the release of contra-insular hormones such as glucagon, somatotropic hormone, and hydrocortisone." (PMID 37760247, 2023). "Increased glucagon signaling leads to dysregulated glucose homeostasis, whereas a decrease in glucagon action improves glycemic index in diabetes independent of insulin sensitivity." (PMID 36866247, 2023). "Type 2 diabetes mellitus (T2DM) is characterized by a range of physiological factors, including insulin resistance, impaired insulin secretion, excess body fat, reduced incretin effect, heightened glucagon release, and abnormal lipid levels." (PMID 37779743, 2023). "Several studies have reported the fluctuation of plasma glucagon levels after food intake in both people with and without diabetes, showing no consistent patterns of glucagon profiles." (PMID 37480216, 2023). "During exercise, circulating insulin stimulates muscle glucose uptake such that in individuals without diabetes, insulin typically decreases and glucagon and other counterregulatory hormones rise." (PMID 36992764, 2022). "Increasing evidence indicates that blocking glucagon and glucagon receptor (GCGR) can relieve hyperglycemia in animals and humans, clearly establishing the important roles of glucagon and GCGR in the pathogenesis of diabetes." (PMID 35784565, 2022). "The median (IQR) glycaemic threshold for the glucagon response in people without diabetes was 3.8 (3.0–3.8) mmol/l." (PMID 35867127, 2022). "Treatments that regulate metabolism, particularly gastrointestinal hormones, are becoming increasingly common; for example, GIP plus glucagon or a triagonist comprising GIP, GLP-1 and glucagon is also being developed for patients with obesity, diabetes or dyslipidaemia." (PMID 35949358, 2022). "Using a systematic review and meta-analysis, we aimed to estimate the mean effect of acute glucagon administration on components of energy balance and glucose homoeostasis in adults without diabetes." (PMID 36123404, 2022). "Despite a lack of consensus on the mechanism, glucagon is known to be one of the key hormones in the pathophysiology of diabetes, and its role throughout the development of T1D should be further studied." (PMID 35642629, 2022). "Gcgr -/- mice were designed to further understand the role of GCGR in the development of diabetes; these mice do not respond to glucagon at any concentration, and their fasting blood glucose levels are lower than those of wild-type mice." (PMID 35784565, 2022). "We therefore conducted a systematic review and random-effects meta-analysis to estimate the mean effects of acute glucagon administration on energy intake, energy expenditure, and subjective hunger in adults without diabetes." (PMID 36123404, 2022). "Clinical studies showing physiological levels of glucagon do not affect adipose tissue lipolysis in either people with or without diabetes support our findings that glucagon does not regulate WAT lipolysis in mice." (PMID 36002172, 2022). "While waiting for a more effective treatment or a diabetes cure, how can individuals with T1D make up for diminished or absent glucagon release during hypoglycemia?" (PMID 36992764, 2022). "The glucagon positive cell numbers of the control group and diabetes group were not significantly different (P > 0.05); the glucagon positive cell number of the GQD or metformin group increased by more than 70% compared to the diabetes group (p < 0.05)." (PMID 35858880, 2022). "In addition, with quartiles of ascending plasma D-dimer, age, SBP, diabetes duration, plasma fibrinogen, and PT were increased, while ALT, TC, LDLC, fasting C-peptide, and glucagon were decreased." (PMID 36082076, 2022). "As well, STZ-induced diabetes did not alter the pattern of distribution between Rab11A and glucagon, but did decrease the colocalization between insulin and Rab11A." (PMID 34923907, 2022).